TES (testin LIM domain protein)
Diseases named in the same sentence as TES in open-access papers (continued):
Sharing a sentence is not in itself a finding about the gene and the disease.
tumor (continued). "In conclusion, this study first identified a tumor suppressor role of TES in CRC." (PMID 27323777, 2016). "Also, reduced TES protein level was detected in 36 (72.0%) of all 50 tumor tissues by Western blot (p = 0.001)." (PMID 20626849, 2010). "Also, reduced TES protein level was detected in 36 (72.0%) of all 50 tumor tissues by western-blot in this study (p = 0.001)." (PMID 20626849, 2010). "Evidence that TES, like other LIM proteins, is shuttled to the nucleus and the presence of additional transcripts of TES, invoke the possibility that the tumour suppressing functions of TES may reside within alternative functions that are yet to be determined." (PMID 20573277, 2010). "Therefore, we hypothesized that TES plays a role as tumor suppressor in GC through interacting with Mena." (PMID 30728082, 2019). "All these findings suggest that TES may present a candidate tumor suppressor gene." (PMID 20626849, 2010). "Among these genes, six (HOXA6, STC2, HSD17B8, TFAP2A, CYP1B1, and HOXC8) were reported to be osteogenesis-/chondrogenesis-related genes, and five (ADRA1A, TSPYL5, TES, TNFRSF10D, and MBP) were reported to be tumor-suppressor genes." (PMID 31889115, 2019). "Loss of FRA7G heterozygosity is seen in many human malignancies, and some studies suggest that genetic and epigenetic alterations of one or more tumor suppressor genes in the FRA7G region, potentially including TES, are involved in multiple malignancies." (PMID 27323777, 2016). "EIF6 and TES both are involved with the cytoskeleton, EIF6 helps link ITGBB4 to the cytoskeleton, and TES is a scaffold protein that has roles in cell adhesion, cell spreading, reorganization of the actin cytoskeleton, regulates cell proliferation, and may act as a tumor suppressor." (PMID 26892349, 2016). "We report that TES re-expression in ALL cell lines results in rapid cell death and decreased proliferation of surviving cells, as previously reported for other tumour cells." (PMID 26985820, 2016). "TES, a LIM domain-containing tumour suppressor gene and component of the focal adhesion complex, is involved in adhesion, motility, cell-to-cell interactions and cell signalling." (PMID 20573277, 2010). "Within the group there are regions coding for genes TES, CAV1 and CAV2, which perform tumor suppressor activities." (PMID 19919683, 2009). "TES protein levels (p < 0.01) and mRNA expression (p < 0.01) were significantly reduced in CRC tissue samples compared with the adjacent tumor-free tissue samples." (PMID 27323777, 2016). "Among 140 pairs of GC samples, decreased TES mRNA level was found in 96 (68.6%) tumor tissues when compared with matched non-tumor tissues (p < 0.001)." (PMID 20626849, 2010).
cancer (15 papers, 2010 to 2024). A tumor composed of atypical neoplastic, often pleomorphic cells that invade other tissues. "HPA analysis showed that the protein levels of LDHA and TES were highly upregulated in cancer tissues compared to normal pancreatic tissue, while those of NDST1, ANKZF1, and SIAH2 were significantly decreased in cancer tissues." (PMID 35935823, 2022). "In these cancer types, the expression of TES was decreased or totally lost by promoter hypermethylation." (PMID 30728082, 2019). "Previous studies showed also high frequency of TES gene HMT in the cancer cells." (PMID 30357755, 2019). "Furthermore, there is a significant adverse correlation between degrees of malignancy in the cancer samples (or the original tumors of the cancer cell lines) and TES protein levels." (PMID 27323777, 2016). "In addition, a profound reduction in growth potential was detected in different cancer cell lines in which TES was overexpressed." (PMID 20626849, 2010). "Thus, TES down-regulation may play important roles in the progression of different types of human cancers." (PMID 30728082, 2019). "Upregulation of TES gene by DAC in ovarian cancer cell line induces cell apoptosis and reduces colony formation preventing from rapid grow of cancer cells." (PMID 30357755, 2019). "In these GBM iPSCs, the widespread resetting of epigenetic methylation occurred in cancer-specific methylation variable positions, the GBM tumor suppressor gene CDKN1C (p57Kip2), and testin LIM domain protein (TES)." (PMID 29259714, 2017). "Co-expressed genes (PXN, ITGA3, TES, and MET) were identified and analyzed by FunRich with CAV1 and CAV2, revealing a significant correlation with focal adhesion (p < 0.001), which has a vital influence on cancer progression." (PMID 36830672, 2023).
haematological neoplasms (1 paper, 2016). "Furthermore our results have been confirmed in subsequent independent studies; for example, TES expression was downregulated in B-lineage ALL; and TES promoter methylation was demonstrated to be specific to ALL in a methylation microarray study of haematological neoplasms." (PMID 26985820, 2016).
TES also shares sentences with these, for which no sentence is quoted: head and neck squamous cell carcinoma (2 papers); astrocytoma (1); COVID-19 (1); glioma (1); hematological malignancies (1); myeloid leukaemias (1); nasopharyngeal carcinoma (1); non-small cell lung carcinoma (1); respiratory disease (1); T-cell lymphomas (1).